SPAG9 (sperm associated antigen 9)
Diseases named in the same sentence as SPAG9 in open-access papers (continued):
Sharing a sentence is not in itself a finding about the gene and the disease.
tumor (continued). "Furthermore, in vivo breast xenograft studies in nude mice revealed that SPAG9 siRNA plasmid injected mice showed significant reduction in tumor growth." (PMID 24330581, 2013). "SPAG9 was first identified from a human testis cDNA library as a member of the CT (cancer testis) antigen family in 1998 and was later found to be involved in the regulation of a variety of tumor invasion and migration factors and viral replication via MAPK signaling." (PMID 35638835, 2022). "SPAG9 may play a key role in reproductive processes, and tumor growth and development." (PMID 24962627, 2014). "Furthermore, in order to investigate whether the reduction of tumor growth is a result of ablation of SPAG9 expression, the xenograft tumors were excised and processed for immunohistochemical staining for SPAG9 protein expression." (PMID 24330581, 2013). "Therefore, we hypothesized that SPAG9 suppresses tumor progression by promoting autophagy in ccRCC." (PMID 37107702, 2023). "Previous research demonstrated that SPAG9 was engaged in JNK pathway, which is closely related to tumor progression." (PMID 26790956, 2016). "Proteins important for tumor cell survival (SND1), proteins known to be expressed by MM cells (PPA1, CCT3, NME1, SPAG9), and a marker for bone resorption (DPYD) were detected at higher levels in the NBM coculture supernatants." (PMID 26545722, 2015). "Notably, MAPK8IP3 (JIP3) had a significant negative correlation with retrograde trafficking genes, whilst SPAG9 (JIP4) had a significant positive correlation, in GP3 and GP4 tumours." (PMID 39217195, 2024). "SPAG9 is involved in the JNK-signaling module and play an important regulatory role in several physiologic and pathological processes, including cell survival, proliferation, apoptosis, and tumor development." (PMID 26790956, 2016). "At present, the role of aberrant-expressed SPAG9 in tumor development has been partly understood, while overexpressed SPAG9 may induce the activation of JNK signaling leading to tumor progression." (PMID 26790956, 2016). "Our results indicated that humoral immune response against SPAG9 was independent of various tumor stages and grades." (PMID 24349057, 2013). "In contrast using RT-PCR and in situ RNA hybridization, SPAG9 mRNA expression was observed in majority of bladder TCC tissues (81%) analyzed irrespective of tumor stages and grades." (PMID 24349057, 2013). "The present study demonstrated that the majority of bladder TCC patients expressed SPAG9 gene and protein irrespective of various tumor stages and grades." (PMID 24349057, 2013). "Essential genes in angiogenesis and invasion, VEGFA, SPAG9, and CDC42, were distinctly upregulated in H3F3B+ tumor cells and clustered in the angiogenesis and invasion pathways, suggesting that H3F3B+ tumor cells may exert angiogenic and invasive effects." (PMID 37430270, 2023). "Interestingly, 82% of superficial non-muscle invasive and 79% of muscle-invasive tumor specimens revealed SPAG9 expression." (PMID 24349057, 2013). "Although the majority of CTA peptides were only found to be unique in one patient, we identified multiple peptides derived from CTA-associated genes that were present in a substantial portion of patients independent of the tumor entity (e.g. ATAD2, SPAG9, ODF2, and KIAA0100)." (PMID 37532709, 2023). "SPAG9 mRNA was detected in 81% bladder TCC tissue specimens by employing RT-PCR among which 82% were of superficial non-muscle invasive and 79% were of muscle-invasive tumor specimens." (PMID 24349057, 2013).
cancer (22 papers, 2013 to 2024). A tumor composed of atypical neoplastic, often pleomorphic cells that invade other tissues. "Since membrane HLA-G expression is linked with STAT3 activation in cancer cells, we chose the membrane localizing SPAG9 protein from the candidate HLA-G protein partners for further investigation." (PMID 36780531, 2023). "High HLA-G and SPAG9 expression has been independently linked to poor survival outcomes in lung and other cancers (49, –51)." (PMID 36780531, 2023). "Sperm Associated Antigen 9 (SPAG9--also known as JIP4 or JLP) is a member of the c-jun N-terminal Kinase interacting protein (JIP) family that is implicated in cancer cell invasion." (PMID 35892887, 2022). "Several studies have reported an association of aberrant SPAG9 expressions in various types of human cancers including breast, thyroid, cervical, and colon carcinoma." (PMID 26790956, 2016). "Recently, we reported an association of sperm-associated antigen 9 (SPAG9) expression, a new member of CT antigen family, in various types of cancers." (PMID 24330581, 2013). "Our previous studies have demonstrated the expression of a novel CT antigen, Sperm associated antigen 9 (SPAG9) in various cancers and showed its association with cellular proliferation, migration and invasion." (PMID 23451156, 2013). "In pan-cancer, SPAG9 expression was significantly associated with poor prognosis." (PMID 37107702, 2023). "Sperm associated antigen 9 (SPAG9), as a novel member of the CT antigen family, was first identified from a human testis cDNA library in 1998, and later found to be aberrantly activated and highly expressed in numerous types of human cancer." (PMID 32776977, 2020). "Our study found that SPAG9 expression predicted opposite clinical outcomes in the pan-cancer and ccRCC patients." (PMID 37107702, 2023). "SPAG9 is a newly identified member of cancer/testis antigens and has been found to induce a specific immune response in several patients with cancer." (PMID 37251077, 2023). "Sperm-associated antigen 9 (SPAG9), a recently characterized oncogene, was associated to the progression of several human cancer and previously correlated to the degree of differentiation and to lymphatic metastasis in ECC." (PMID 36203482, 2022). "Several type of cancers, including bladder, breast, prostate, renal and gastrointestinal, exhibit ectopic SPAG9 expression." (PMID 35892887, 2022). "Promising new splice variants with a potential link with cancer are CSF1, PLOD2, SLK, SPAG9 and TSC2." (PMID 33845831, 2021). "Our histopathological analysis showed that two patients were found to have poorly differentiated carcinoma with SPAG9 protein expression." (PMID 34493268, 2021). "SPAG9 was highly expressed in a variety of human cancer, including colorectal carcinoma, renal cell carcinoma, cervical, thyroid, and breast cancer." (PMID 32776977, 2020). "These novel findings define the mechanism of KSHV induction of the SPAG9/JNK/VEGFA pathway and establish the scientific basis for targeting this pathway for treating KSHV-associated cancers." (PMID 32776977, 2020). "Sperm associated antigen 9 (SPAG9) is a well-characterized oncoprotein, highly expressed in a variety of human cancer." (PMID 32776977, 2020). "Further, SPAG9 gene silencing also resulted in reduction in cellular growth, and migration and invasion ability of cancer cells in vitro." (PMID 24349057, 2013). "In the present study, we demonstrated generation of humoral response against SPAG9 in a significant number of bladder TCC patients consistent with the known immunogenicity of this antigen in other cancers." (PMID 24349057, 2013). "Further, we investigated SPAG9 protein expression employing Western blotting which confirmed SPAG9 expression in all cancer cells." (PMID 24349057, 2013). "Thus, we next explored the possibility of preventing BM by targeting SPAG9 in primary cancers with a high predilection for BM." (PMID 36780531, 2023).
cancer (continued). "Since SPAG9 has been shown in some cancers to regulate sensitivity to 5-FU, cetuximab and radiotherapy, evaluating the relevance of SPAG9 expression to the treatment of epidermal tumors could be informative." (PMID 35892887, 2022). "Several studies have reported the overexpression of SPAG9 gene product in many cancers." (PMID 27655714, 2016). "Collectively, IIF and FACS data suggested that SPAG9 may be a potential target for cancer immunotherapeutics." (PMID 24330581, 2013). "Using plasmid-based small interfering RNA (siRNA) approach to knockdown SPAG9, we demonstrated significant reduction in cellular proliferation, colony forming ability, cellular migration, invasion and wound healing capacity in different types of cancers." (PMID 24330581, 2013). "Subsequently, in fixed cancer cells, flow cytometric analysis revealed significant increase in displacement of fluorescence on the x axis when probed with anti-SPAG9 antibody indicating surface localization of SPAG9 protein in all cancer cells (green histogram)." (PMID 24349057, 2013). "However, it is not known whether high levels of HLA-G and/or SPAG9 in primary cancers could predict patients at risk of developing BM." (PMID 36780531, 2023). "Previous studies showed that SPAG9 promotes proliferation and migration in both ccRCC and BLCA cell lines, while SPAG9 plays opposite prognostic roles in these two cancers." (PMID 37107702, 2023). "Among the genes, SPAG9, NME1, and NME2 are involved in regulating the proliferation of cancer cells." (PMID 30901931, 2019). "SPAG9 and PRK1 colocalize in human cancer tissue and are required for p38-phosphorylation and cell migration." (PMID 25504435, 2014). "At the single nucleotide polymorphism (SNP) mutation level and transcriptional level, we found that MAP4, YWHAG, KSR2, SPAG9, and CEP250 gene-related loci are different in cancer and paracancer tissues, and MAP4, YWHAG, CEP135, and CEP250 differed significantly at the transcriptional level." (PMID 36705386, 2023). "We further probed SPAG9 co-localization with various cell organelles by using multiple markers for Golgi body (GM130), endoplasmic reticulum (calnexin), nuclear envelope (lamin A/C) and mitochondria (MTCO2) in high grade invasive UM-UC-3 cancer cells." (PMID 24349057, 2013). "RT-PCR analysis revealed that the SPAG9 mRNA expression was detected in all cancer cell lines but not in NHU cell line." (PMID 24349057, 2013). "It is possible that the generation of SPAG9 humoral response depends upon the MHC genetics of the cancer patients classifying them as responders or non-responders to SPAG9 antigenicity." (PMID 24349057, 2013). "Hence, these findings suggest that SPAG9 protein expression may have important implications in vaccine development by employing active or passive immunization or dendritic cells based approaches for better cancer management programmes and warrants future studies." (PMID 24349057, 2013). "SPAG9 expression was also bound up with circulating anti-SPAG9 antibodies, indicating that SPAG9 could be a promising noninvasive serum biomarker for early diagnosis and cancer management." (PMID 32776977, 2020).
neurodevelopmental disorder (1 paper, 2025). A behavioral and cognitive disorder with onset during the developmental period that involves impaired or aberrant development of intellectual, motor, or social functions. "SPAG9 has been associated with functional clusters known to beassociated with neurodevelopmental disorders (NDDs) including chromatinorganization, nervous system development and revealed co-expression/ interactionwith other known candidate genes." (PMID 39846792, 2025).
SPAG9 also shares sentences with these, for which no sentence is quoted: colorectal cancer (4 papers); thyroid cancer (4); colon cancer (3); renal cell carcinoma (3); bladder transitional cell carcinoma (2); chronic myeloid leukemia (2); Infertility (2); Parkinson disease (2); acute lymphoblastic leukemia (1); Alzheimer disease (1); ameloblastic carcinoma (1); anaplastic thyroid carcinoma (1); breast (1); Clear-Cell Renal Cell Carcinoma (1); cystinosis (1); diabetes (1); endocervical adenocarcinoma (1); genetic disorders (1); Hepatitis (1); Insulin resistance (1); Kaposi's sarcoma (1); kidney chromophobe carcinoma (1); kidney diseases (1); Lysosomal disease (1); lysosomal storage disease (1); nasopharynx cancer (1); non-melanoma skin carcinoma (1); Obesity (1); oculocutaneous albinism (1); osteosarcoma (1).
A further 10 diseases each share a sentence with SPAG9 in 1 paper.